RNF11 (ring finger protein 11)
Diseases named in the same sentence as RNF11 in open-access papers:
RNF11 is named in the same sentence as 31 diseases in open-access papers, as found by Europe PMC text mining. Sharing a sentence is not in itself a finding about the gene and the disease. The quoted sentences say what the papers report.
breast carcinoma (8 papers, 2003 to 2025). "According to previous reports, RING finger protein 11 (RNF11), a 154 amino acid protein belonging to the E3 ubiquitin ligase family, is strongly associated with human breast cancer and hepatocellular carcinoma." (PMID 36238643, 2022). "RNF11 is abnormally expressed in breast cancer and can promote the malignant development of breast cancer." (PMID 33123581, 2020). "Here, we investigated RNF11 protein expression in an array of 125 human primary tumours, including mammary carcinomas, and studied potential protein binding partners." (PMID 14562029, 2003). "Indeed, AMSH mRNA has been found differentially expressed in breast cancer cell lines and the RNF11 protein has been found overexpressed in invasive breast cancers." (PMID 33187263, 2020). "Moreover, RNF11 knockdown reduces cell migration and proliferation in the 4T1 and 4T07 breast cancer cell lines, and specifically decreases the expression of genes promoting tumor growth and metastasis." (PMID 33187263, 2020). "For example, Smurf2 has been shown to target ring finger protein 11 (RNF11), Smurf1, and connector enhancer of kinase suppressor of Ras 2 (CNKSR2) for ubiquitination and degradation in breast cancer." (PMID 40978141, 2025). "Other researchers have reported associations of RNF11 with glutathione S-transferase -tagged Itch in breast cancer cell lines, tagged RNF11 with tagged TAX1BP1 and A20 in HEK cells and RNF11 with A20, TAX1BP1 and RIP1 in mouse embryonic fibroblasts and blood-derived macrophages." (PMID 22507528, 2012).
hepatocellular carcinoma (4 papers, 2003 to 2022). A malignant tumor that arises from hepatocytes. "For example, miR-425-5p is significantly increased in hepatocellular carcinoma (HCC) tissues and is closely related to the poor prognosis of patients with HCC, which as an oncogene promotes the proliferation and migration of HCC cells via RNF11 or FOXD3." (PMID 34686190, 2021). "This relief of inhibition depends upon the wild-type PY motif in RNF11, as the RNF11 mtPY does not produce this effect when contransfected with the Smurf2 vector in TGFβ-treated HepG2 human hepatoma cells." (PMID 14562029, 2003).
neuroblastoma (3 papers, 2012 to 2020). Neuroblastoma (NB) is the most common solid, extracranial childhood tumor. "In contrast, we have shown in this study that V5-Y40AR associated with endogenous Itch in neuroblastoma cells, although Itch immunoreactivity was reduced compared to wild-type RNF11." (PMID 22507528, 2012). "Reduced RNF11 expression resulted in persistent NF-κB signaling, and association of RNF11 with the A20 ubiquitin-editing protein complex was demonstrated in neuroblastoma cells and primary cortical neuron cultures." (PMID 22507528, 2012). "In addition, we expand the miR-17∼92 regulatory network controlling TGFß signaling in neuroblastoma with the ring finger protein 11 encoding gene RNF11, which was previously shown to be targeted by the miR-17∼92 member miR-19b." (PMID 23308108, 2013). "The role of RNF11 in the TGFβ pathway is of particular interest in neuroblastoma given our previous finding that the miR-17∼92 cluster components target TGFBR2 and SMAD2 as well as TGFβ downstream regulated genes CDKN1A, ITGA4, and SERPINE1." (PMID 23308108, 2013). "Reciprocal co-IPs revealed that RNF11 was enriched in FLAG pull-down assays for FLAG-A20, indicating that RNF11 and A20 associate in neuroblastoma cells." (PMID 22507528, 2012). "The role of RNF11 in counteracting the persistent NF-κB activation has been validated in several cell lines, particularly in neuroblastoma cells, primary cortical neurons and microglial cells, where it has been shown to protect against LPS-induced cell cytotoxicity." (PMID 33187263, 2020). "Survival analysis in the same cohort of 101 neuroblastoma tumors showed association of decreased mRNA expression levels of both RGS5 and RNF11 with poor survival (p = 4.8E-2; p = 6.4E-4), which is in line with the observed association of both genes with MYCN expression." (PMID 23308108, 2013). "Luciferase assays were employed to assess NF-κB activity under targeted short hairpin RNA (shRNA) knockdown of RNF11 in human neuroblastoma cells and murine primary neurons, which suggested that RNF11 acts as a negative regulator of canonical neuronal NF-κB signaling." (PMID 22507528, 2012). "Furthermore, depletion of RNF11 resulted in aberrant regulation of inflammatory signaling in neuroblastoma cells and primary cortical neurons." (PMID 22507528, 2012). "In this study, we investigated the role of neuronal RNF11 as a component of the A20 ubiquitin-editing complex in regulating TNF-α-induced canonical NF-κB activity by targeted knockdown of endogenous RNF11 in human neuroblastoma cells and primary neuronal cultures." (PMID 22507528, 2012).
Parkinson disease (3 papers, 2012 to 2016). A progressive degenerative disorder of the central nervous system characterized by loss of dopamine producing neurons in the substantia nigra and the presence of Lewy bodies in the substantia nigra and locus coeruleus. "RNF11 is a 154-amino-acid protein which exhibits differential expression in cancer as well as in Parkinson's disease." (PMID 26937036, 2016). "RNF11 (ring finger protein 11) was suggested to play major role in the Parkinson's disease pathology since it was found highly enriched in SN dopamergic neurons as well as its co-localization within Lewy bodies (abnormal aggregates of protein) in PD brains." (PMID 24688734, 2013). "RNF11 is a 154-amino acid protein with differential expression in cancer, including breast, pancreatic and colon, as well as in Parkinson disease (PD)." (PMID 22507528, 2012). "RNF11 is robustly expressed in neurons and colocalizes with a population of α-synuclein-positive Lewy bodies and neurites in Parkinson disease patients." (PMID 22507528, 2012).
breast tumors (2 papers, 2003 to 2013). "RING finger protein 11 (RNF11) is an evolutionarily conserved 154 amino acid protein that was originally found to be overexpressed in breast tumors." (PMID 23308279, 2013). "The RNF11 gene was originally cloned as T2A10, a cDNA fragment from our library enriched for breast tumour-specific mRNAs." (PMID 14562029, 2003).
gastric cancer (2 papers, 2020). A primary or metastatic malignant neoplasm involving the stomach. "Furthermore, we suggested RNF11 expression as a predictive biomarker for gefitinib treatment in gastric cancer." (PMID 32070411, 2020). "Interestingly, small interfering RNA (siRNA)-mediated knockdown of RNF11 in two different RNF11high gastric cancer cells (SNU5 and NCI-N87) conferred increased sensitivities to gefitinib." (PMID 32070411, 2020). "The recent report that, in two different gastric cancer cell lines, SNU5 and NCI-N87, the knockdown of RNF11 increases the sensitivity to gefitinib treatment strongly suggests RNF11 as a promising therapeutically exploitable target." (PMID 33187263, 2020).
melanoma (2 papers, 2020 to 2023). A malignant, usually aggressive tumor composed of atypical, neoplastic melanocytes. "Fifthly, we identified ‘4‐genes risk prediction model’ (RNF11, NUDT21, RAB31, and ARID4B) and the ‘glycolysis‐prognosis‐10‐gene set’ that each confers independent prognostic significance for melanoma." (PMID 37356089, 2023). "RNF11 disruption by insertional mutagenesis and knockdown both impair the metastatic potential of murine melanoma B16F10 cells in vitro and in vivo, respectively." (PMID 33187263, 2020). "Consistently, RNF11 overexpression increases the migratory potential of melanoma cells." (PMID 33187263, 2020).
prostate carcinoma (2 papers, 2003 to 2016). A carcinoma that arises from epithelial cells of the prostate gland. "This combination could thus be interesting to test in breast- and prostate cancer, due to the previously published association between RNF11 expression and these tumor types." (PMID 27689322, 2016). "Modest RNF11 expression was seen in 63% of the head and neck tumours, and 57% of the lung tumours, whereas renal and prostate carcinomas stained only weakly positive for RNF11 protein (∼10%)." (PMID 14562029, 2003).
selenium deficiency (2 papers, 2020 to 2023). A nutritional deficiency disease resulting from inadequate selenium levels in the body, which can lead to impaired function of selenoproteins essential for antioxidant defense and thyroid hormone metabolism. "As a negative impact, it has been reported that miR-200a-5p promoted selenium deficiency-induced myocardial necrosis by targeting ring finger protein 11 (RNF11), which is known to negatively regulate NF-κB signaling." (PMID 37106699, 2023). "miR-200a-5p and its target gene Rnf11 is involved in selenium deficiency-induced cardiac necrosis via MAPK activation." (PMID 32655553, 2020).
viral infections (2 papers, 2013 to 2016). "It is also unclear what regulates the interactions between A20, TAX1BP1, ABIN1 and RNF11 during virus infection to assemble the A20 antiviral complex." (PMID 23308279, 2013). "Together, this study suggests that RNF11 is a novel inhibitor of antiviral signaling that cooperates with TAX1BP1 to restrict IFN production during virus infection." (PMID 23308279, 2013). "Collectively, these data suggest that RNF11 is recruited to TBK1 and IKKi upon virus infection and attenuates their Lys63-linked polyubiquitination to block IFN-β production." (PMID 23308279, 2013). "Since multiple E3 ligases have been proposed to conjugate ubiquitin onto TBK1 during virus infection including TRAF3, Mind bomb and Nrdp1, it is possible that RNF11 (and the A20 complex) also blocks TBK1/IKKi interactions with Mind bomb and Nrdp1." (PMID 23308279, 2013). "Therefore, RNF11 is likely recruited to both TBK1 and IKKi only when they are activated in response to virus infection." (PMID 23308279, 2013). "Since RNF11 also blocks type I IFN production, these animals may be more resistant to virus infection." (PMID 23308279, 2013).
acute myeloid leukemia (1 paper, 2020). Acute myeloid leukemia (AML) is a group of neoplasms arising from precursor cells committed to the myeloid cell-line differentiation. "Recently, RNF11 has been found to be ubiquitinated and sumoylated in two human acute myeloid leukemia (AML) cell lines." (PMID 33187263, 2020).
bladder cancer (1 paper, 2026). "Functional characterization showed that RNF11 regulates proliferation and migration of bladder cancer." (PMID 41624768, 2026).
colon cancer (1 paper, 2003). "RNF11 was markedly overexpressed in breast and to a somewhat lesser extent in pancreatic as well as colon cancer samples, whereas it was only weakly expressed in prostate and renal cell carcinomas." (PMID 14562029, 2003).
head and neck cancer (1 paper, 2003). A primary or metastatic malignant neoplasm affecting the head and neck. "Although RNF11 protein expression was predominantly located in the cytoplasm in all eight tissue types on the TMA, some nuclear RNF11 accumulation was observed in lung, renal, and head and neck cancers." (PMID 14562029, 2003).
heart failure (1 paper, 2024). Inability of the heart to pump blood at an adequate rate to meet tissue metabolic requirements. "Something similar occurs with the RNF11 locus, although this does not reach genome-wide significance for heart failure (P = 3.2 × 10−6)." (PMID 38523678, 2024).
invasive breast carcinoma (1 paper, 2003). A carcinoma that infiltrates the breast parenchyma. "This is particularly relevant in the light of the observed overexpression of RNF11 in invasive breast cancers and its affects on TGFβ responsive gene activation." (PMID 14562029, 2003).
lung carcinoma (1 paper, 2003). "Comparison of RNF11 expression between breast, prostate, head and neck, kidney, colon and lung cancers revealed that the majority of our tumour array specimens produced clear immunostaining without any detectable background, and the morphology of the tissues was well preserved." (PMID 14562029, 2003).
Obesity (1 paper, 2016). Accumulation of substantial excess body fat. "Thus, RNF11 represent a further molecular detail how hypothalamic inflammation may trigger leptin resistance and obesity in the very early days of high caloric intake." (PMID 27551276, 2016).
tumor (8 papers, 2003 to 2026). "Conversely, siRNA-mediated knockdown of RNF11 sensitized tumor cells, including tubular-type tumors to gefitinib." (PMID 32070411, 2020). "This connection appears to be particularly significant, since RNF11 is overexpressed in several tumors, even though its role as tumor growth inhibitor or promoter is still controversial." (PMID 33187263, 2020). "During the early stages of tumorigenesis, RNF11 overexpression appears to act as an inhibitor of cellular proliferation and, thus, counteracts tumor growth." (PMID 33187263, 2020). "RNF11 protein expression in primary tumours was monitored by IHC using affinity purified anti-human RNF11 polyclonal antibody on a TMA composed of duplicate punches from 125 primary tumours representing eight different histologies." (PMID 14562029, 2003). "The specificity of RNF11 staining in the arrayed tumour tissues was confirmed by probing control sections with RNF11 antibody that had been preincubated with the hexa-decapeptide used for immunisation." (PMID 14562029, 2003). "TMA technology allowed for a rapid and simultaneous analysis of RNF11 protein expression in 125 primary tumours microarrayed in duplicate by immunohistochemical staining using anti-RNF11 antibody." (PMID 14562029, 2003). "The expression pattern of RNF11 in human primary tumours is interesting when compared to Smurf2 in that head and neck tumours including oesophageal SCC samples expressed RNF11 in 63% of the surveyed cases." (PMID 14562029, 2003). "Moreover, RNF11 can directly enhance TGFb signaling through a direct association with SMAD4 and promote the malignant development of tumor cells." (PMID 33123581, 2020). "RNF11 is a member of the ubiquitin ligase family and capable of modulating protein function through ubiquitination and perhaps through sumoylation, which may play an important role in tumor formation." (PMID 33123581, 2020). "Through LASSO-Cox regression and stepwise selection, we constructed a four-gene Tumor-Progressing Fibroblast Riskscore model comprising FOXA1, TBX3, LRIG1, and RNF11." (PMID 41624768, 2026).
cancer (5 papers, 2003 to 2021). A tumor composed of atypical neoplastic, often pleomorphic cells that invade other tissues. "All of this being considered, these data strongly suggest that targeting RNF11 may be therapeutically beneficial, especially in multiple types of cancer." (PMID 33187263, 2020). "However, at later stages of tumorigenesis, RNF11 seems to promote the migratory and invasive properties of cancer cells by inducing the epithelial-mesenchymal transition (EMT)." (PMID 33187263, 2020). "Notably, the negative feedback loop can be disrupted by Ring finger protein 11 (RNF11) activity, which is overexpressed in cancer cells." (PMID 32733916, 2020). "WWP1 contains two WW domains that have been shown to recruit and modulate the activity of cancer related proteins like Runt-related transcription factor 2 (RUNX2), RING finger protein 11 (RNF11) and large tumor suppressor kinase 1 (LATS1) via their proline-rich (PY) motifs." (PMID 33869064, 2021).
infection (2 papers, 2019 to 2020). The state of being infected such as from the introduction of a foreign agent such as serum, vaccine, antigenic substance or organism. "Moreover, different virulence NDV strains infection resulted in a similar suppression of these two proteins expression, indicated that a virulence-independent regulation of RNF11 and ZMYND11 during NDV infection in vitro." (PMID 31507581, 2019). "Gene silencing showed that downregulation of A20, TAX1BP1, ABIN1, and ITCH but not RNF11, increased apoptosis in cells infected with HRSV at later times post-infection." (PMID 32102364, 2020).
nervous system disease (2 papers, 2012 to 2022). "Inflammation is tightly associated with NF-κB signaling as well as with neurological disease; therefore, we investigated whether RNF11 is linked to inflammatory response induction." (PMID 22507528, 2012). "The nervous system disease class consists of proteins APP, DYNC1H1, DYNC1I2, HINT1, LSM2, RNF11, SNCA in between 30% and 40% association." (PMID 34918006, 2022).
neurodegenerative disease (2 papers, 2012 to 2020). A disorder of the central nervous system characterized by gradual and progressive loss of neural tissue and neurologic function. "Reduced or functionally compromised RNF11 could influence NF-κB-associated neuronal functions, including exaggerated inflammatory responses that may have implications for neurodegenerative disease pathogenesis and progression." (PMID 22507528, 2012). "We examined the functional role of RNF11 with respect to canonical NF-κB signaling in neurons to gain understanding of the tight association of inflammatory pathways, including NF-κB, with the pathogenesis of neurodegenerative diseases." (PMID 22507528, 2012). "Our future studies will focus on investigating the role of RNF11 as a regulator of neuroinflammation in animal models of neurodegenerative diseases." (PMID 22507528, 2012). "Given the mounting evidence that neuroinflammation is heightened in neurodegenerative diseases, we conclude that functionally compromised or reduced expression of RNF11 could result in persistent NF-κB activation and could promote chronic neuroinflammation." (PMID 22507528, 2012).
RNF11 also shares sentences with these, for which no sentence is quoted: B cell lymphoma (1 paper); dwarfism (1); fibromyalgia (1); head and neck tumours (1); Hypertension (1); meningioma (1); Myocardial necrosis (1); renal cell carcinoma (1).